IL6 (interleukin 6)
Diseases named in the same sentence as IL6 in open-access papers (continued):
Sharing a sentence is not in itself a finding about the gene and the disease.
Hypertension (continued). "Moreover, one cannot exclude that in the context of cardiovascular ageing and hypertension, IL-6 might be involved in compensatory response aimed at preserving vascular homeostasis." (PMID 38720047, 2024). "The eQTL results can account for the different association of IL-6 -174C > G and -572G > C with hypertension risk, as the -174G allele leads to the lower expression of IL-6, while the -572G > C polymorphism does not affect the expression of IL-6 in eQTL analysis." (PMID 37920615, 2023). "As for the IL-6 gene rs1800796 (-572G > C) polymorphism, no substantial associations were found in all genetic models, indicating the mutation did not contribute to the occurrence of hypertension." (PMID 37920615, 2023). "However, the -572G > C variant does not lead to the change of IL-6 gene expression and the development of hypertension." (PMID 37920615, 2023). "Furthermore, IL-6 levels correlated with the incidence of hypertension and hypercholesterolemia." (PMID 37629496, 2023). "Therefore, both kidney-resident and bone-marrow-derived macrophages may be able to augment renal cortical IL-6 levels in Ang II-dependent hypertension." (PMID 35887028, 2022). "The signaling pathways linking S1P and ROS generation could be a bridge between cardiovascular and immune systems, which might be involved in the pathogenesis of hypertension, especially given that sortilin regulates the secretion of proinflammatory cytokines (IL-6 and interferon-γ) by immune cells." (PMID 36312293, 2022). "Serum levels of inflammatory cytokines such as IL-6, high-sensitivity C-reactive protein as well as uric acids have been considered as predictors of severe outcomes in patients with coronary artery disease (CAD) associated with hypertension (HTN) and Type2 Diabetes Mellitus (T2DM)." (PMID 37323554, 2022). "Additionally, three studies reported immunological factors alteration in hypertension: pro-inflammatory cytokines, including TNF, IL-6, etc., and compounds, e.g., LPS, were increased; anti-inflammatory compounds, such as 3,4,5-trimethoxycinnamic acid, were decreased in hypertension." (PMID 34055933, 2021). "The inflammatory process in hypertension is characterized by increased levels of local inflammatory cytokines such as IL-6, IL-1β, TNF-α, and ICAM-1, which are highly correlated with an increased risk for hypertension, and may be useful diagnostic tools for hypertension in the future." (PMID 33906674, 2021). "Furthermore, we observed a significant association between the levels of proinflammatory cytokines and the levels of key elements in overweight women, in whom Il-6 levels were related to Na levels, which may contribute to the development of hypertension." (PMID 34890370, 2021). "In addition to C-reactive protein and IL-6, TNF-α, IL-1β, IL-18, and CCL2 cytokine levels also appear to be increased in hypertension and may confer risk of developing the disease." (PMID 34698811, 2021). "The expression levels of a variety of other inflammatory markers also changed in hypertensive patients, representative ones are TNF-α and IL-6, suggesting that the occurrence of hypertension may be the result of the combined action of a variety of inflammatory factors." (PMID 32322161, 2020). "In addition, baicalin treatment attenuated hypertension-associated intestinal hyperpermeability and decreased the serum levels of inflammatory indicators such as high-sensitivity C-reactive protein (hs-CRP), interleukin 1 beta, and IL-6 in the SHRs." (PMID 31719823, 2019). "IL-6 may even show promise as a biomarker; several studies have proposed increased IL-6 and TNF-α serum levels as independent risk factors for the development of high blood pressure in apparently healthy patients." (PMID 31186952, 2019). "Moreover, overstimulation of IL-6 production can also induce pulmonary high blood pressure in mice." (PMID 31703282, 2019).
Hypertension (continued). "Of note, IL-6 quartiles were found to be strongly associated with the risk of developing hypertension in the Nurses Health Study, and mice lacking this cytokine are protected against Ang II-induced hypertension." (PMID 29800237, 2018). "The presence CG genotype for 174 G/C of IL-6 in patients with hypertension may serve as a predictor of diastolic heart failure with inflammatory background and motivate to start with also non-pharmacological therapies reducing inflammation like smoking cessation and regular physical training." (PMID 28827564, 2017). "Thus, the limited sample size, small BMI ranges, normal blood glucose and age and potential effects of hypertension may explain the similarity on IL-6 and TNF-α in levels." (PMID 29245360, 2017). "For example, plasma IL-6 concentrations correlate with blood pressure, plasma angiotensin II levels, and vascular hypertrophy, suggesting an important role of IL-6 in the development and maintenance of hypertension, particularly that mediated by angiotensin II." (PMID 29186034, 2017). "However, the role of endogenous IL-6 in hypertension-induced cardiac fibrosis was unclear, and the cell type producing IL-6 was unknown." (PMID 22574112, 2012). "The authors speculated that the IL-6 stimulates sFlt-1 and sEng production by trophoblast cells in an autocrine manner by JAK-STAT signaling, and that increased IL-6 contributes to antibody-mediated hypertension in women with PE via IL-6-induced stimulation of sFlt-1 production by trophoblasts." (PMID 22269218, 2012). "However, the role of endogenous IL-6 in hypertension-induced myocardial fibrosis is unclear." (PMID 22574112, 2012). "For future studies, clinical measures such as hypertension or BMI could be useful covariates when investigating genetic inflammatory biomarkers such as IL-6; however, the relevance of hypertension might be of greater relevance in clinical samples than in our healthy cohort." (PMID 22695063, 2012). "In the PE rat model, downregulation of GCLM and SNAP23 and upregulation of RHOT2 were significantly correlated with clinical phenotypes such as hypertension and proteinuria, as well as changes in placental inflammatory factor levels (TNF-α, IL-1β, IL-6)." (PMID 41953137, 2026). "Inhibiting the IL-6/JAK/STAT3 pathway reduces Th17 activity, alleviating vascular inflammation and damage in hypertension." (PMID 40079010, 2025). "Central to this inflammatory cascade are cytokines including interleukin (IL)-6 and tumor necrosis factor-alpha (TNF-α), which are elevated in individuals with hypertension." (PMID 40863231, 2025). "However, a significant reduction in the synthesis of IL6 was observed in the testes of rats with hypertension subjected to HIIT, demonstrating that this modality of physical training can effectively reduce the levels of testicular inflammatory mediators caused by hypertension." (PMID 40357058, 2025). "Multivariate statistical analysis revealed the volume of drained FP, the presence of hypertension, and cerebrovascular disease or the use of angiotensin-converting enzyme inhibitors or sartans as predictors of POAF in addition to IL-6 and age." (PMID 40002559, 2025). "Individuals with hypertension often have elevated levels of pro-inflammatory markers, such as C-reactive protein (CRP), interleukin-6 (IL-6), TNF-α, and reactive oxygen species (ROS)." (PMID 39940640, 2025). "Activation of this pathway can lead to increased expression of pro-inflammatory cytokines such as interleukin-6 (IL-6) and tumor necrosis factor-alpha (TNF-α), contributing to vascular inflammation and hypertension." (PMID 41551943, 2025). "This upregulates the transcription of inflammatory factors (such as IL-6) and adhesion molecules (such as ICAM-1, VCAM-1, and E-selectin), leading to the development of vascular inflammation and hypertension." (PMID 41373978, 2025).
Hypertension (continued). "Morinda officinalis oligosaccharides suppressed the secretion of IL-6, IL-1β, and TNFα in LPD-stimulated astrocytes and exerted antidepressant activity in hypertension rats." (PMID 40108901, 2025). "TREM2 KO hypertensive mice with Pb exposure exhibited further upregulated proinflammatory cytokines (IL-6, TNF-α) and downregulated anti-inflammatory comparing with C57 mice in the Pb + hypertension group." (PMID 39853035, 2025). "Oyarce and Iturriaga discovered that the mRNA levels of IL-1β, IL-6, and TNF-α were increased in the NTS of rats with hypertension following 21 days of IH." (PMID 38276286, 2024). "Adiposity-related pro-inflammatory markers such as leptin, interleukin-6 (IL-6), and tumour necrosis factor-α (TNF-α), and lower levels of anti-inflammatory markers, such as adiponectin play a role in the development of hypertension." (PMID 37872379, 2024). "Log-transformed IL-6 and CRP levels also remained significantly higher after correcting for renal function, smoking and hypertension." (PMID 39012360, 2024). "In clinical studies, middle-aged and elderly participants with hypertension who were administered a daily dose of 2 g EPA + DHA for 90 days exhibited reduced plasma levels of CRP and Tnfα, while Il6 levels remained unaffected." (PMID 39683572, 2024). "The objective of this study is to demonstrate that activation of microglial CB2 receptors can effectively reduce the levels of TNF-α, IL-1β, and IL-6 in the paraventricular nucleus (PVN) through inhibiting aerobic glycolysis, thereby relieving hypertension." (PMID 38540753, 2024). "At the same time, hypertension will also lead to increased inflammation, and the interaction between CRP, IL-1, IL-6 and TNF-α and blood pressure will eventually lead to an increased risk of CA." (PMID 39464793, 2024). "Several pro-inflammatory/inflammatory markers, including IL-1β, IL-6, IL-8, IL-17, IL-23, interferon-γ, CXCL10, and TNF-α, were found to be elevated in SAS patients with hypertension." (PMID 38276286, 2024). "For example, hypertensive animals and human patients have increased levels of IL-1β, IL-6, IL-17, TNF-α, CCL-2, C-reactive protein, and adhesion molecules, while immunosuppression attenuates hypertension." (PMID 39513878, 2024). "A well‐established connection exists between essential hypertension and key inflammatory markers, including tumor necrosis factor‐alpha (TNF‐α), interleukin‐6 (IL‐6), and C‐reactive protein." (PMID 38504425, 2024). "While the significance of these correlations was lost after adjustment for age, sex, BMI, and IL-6 or CRP, adjustment for age, sex, and statins as well as for age, sex, and hypertension made the correlation between EL and IDL-TG/IDL-apoB insignificant." (PMID 37445857, 2023). "IL-6 (p = 0.035), IL-8 (p <0.0001), IL-10 (p = 0.009), and TNF-α (p <0.0001) serum levels were significantly higher in patients with arterial hypertension." (PMID 37969879, 2023). "Among the mediators involved in the pathophysiology of arterial hypertension within the MetS are tumour necrosis factor-α (TNF-α) and interleukin-6 (IL-6)." (PMID 36677012, 2023). "Previously, it has been shown that IL-6 and TNF-α, positively correlated with blood pressure in pregnancy induced hypertension." (PMID 37745103, 2023). "ROS promotes IL-6, TNF-α, and AT-1expression by activating NF-κB leading to hypertension and anxiety." (PMID 37273529, 2023). "Two of the prominent pro-inflammatory cytokines, TNF-α and IL-6 are elevated in conditions resulting from heightened SNS activation, such as T2D and hypertension." (PMID 36979798, 2023). "Hypertension induced the increase in TNF-α, IL-1β, and IL-6 levels in the brain and serum, and CUMS further increased the levels of these pro-inflammatory cytokines." (PMID 36765376, 2023). "Chronic low-grade inflammation, characterized by increases in proinflammatory biomarkers such as IL-6 and hs-CRP, contributes to the development of essential hypertension." (PMID 37324636, 2023).
Hypertension (continued). "The deletion of IL-6 can prevent the activity of the JAK2/STAT3 pathway, which plays a role in Ang II-induced hypertension." (PMID 35402550, 2022). "Inflammatory cytokines like IL-6, TNF-α, IFN-γ, and IL-17 released by immune cells significantly increase in patients with hypertension, and the levels of plasma IL-6 and TNF- α was positively correlated with blood pressure and end-organ damage." (PMID 36713422, 2022). "Elevated IL-6 levels on POD2 as well as smoking, drinking, hypertension, prolonged mechanical ventilation and ICU stay were all independent risk factors for PP." (PMID 35794529, 2022). "In our study, we found that renal cortex IL-6 increased in the LLL group (which is compatible with previous reports), suggesting that inflammation plays an important role in programming hypertension." (PMID 35955421, 2022). "The expression or secretion of MCP-1, IL-6, TGF-β and IL-10 are influenced by microbiota or its metabolite and have potential effect on hypertension." (PMID 36195874, 2022). "In the past few years, important roles of at least 5 cytokines have been identified in hypertension, including IL-17, interferon γ (IFN-γ), TNF-α, IL-6, and IL-10." (PMID 35528508, 2022). "Circulating levels of harmful proinflammatory cytokines, including interleukin-1β (IL-1β), interleukin-6 (IL-6), and tumor necrosis factor alpha (TNF-α) trigger to the development of hypertension and renal and cardiovascular disorders in humans." (PMID 36683859, 2022). "We also observed that ASC + LOS significantly detained hypertension and renal interstitial macrophage infiltration more effectively than ASC or LOS alone, also normalizing the renal expression of IL-6, a potent proinflammatory mediator." (PMID 35371263, 2022). "There was also a higher proportion of patients with hypertension and type-2 diabetes (T2DM) and a trend toward a higher proportion of obese patients in the group with higher levels of IL-6." (PMID 36028849, 2022). "It has been observed that the rise of cytokines such as IL-6 and CCL2 in the high-salt diet-induced hypertension rat model is connected with the NLRP3 inflammatory mechanism." (PMID 36035920, 2022). "34.9% of the participants had hypertension, 61.5% had hypercholesterolemia, 57.8% had hypertriglyceridemia and 11.9% had inflammation (high levels of CRP or IL-6)." (PMID 34991564, 2022). "Expression of IL-10, IL-8, IL-1β, IL-6, IL-4, TGFβ1, TNFα and GM-CSF significantly decreased in the CSWT group compared with the hypertension group." (PMID 36362064, 2022). "Monocytes from patients with essential hypertension are preactivated, producing greater amounts of IL-1β, TNF and IL-6 following ex vivo stimulation with angiotensin II or LPS than monocytes from healthy controls." (PMID 35743626, 2022). "A number of previous observational studies reported associations between indicators of inflammation, such as C-reactive protein, interleukin-6, interleukin-8, WBC count, neutrophil count, neutrophil to lymphocyte ratio, and incidence of hypertension." (PMID 33529192, 2021). "Nevertheless, Yanget al. declared that patients with hypertension came with highly detected inflammatory markers such as CRP (p=0.024), Procalcitonin (p=0.017) and IL6 (p=0.017)." (PMID 34912542, 2021). "The aorta mRNA relative expression levels of IL-6, TNF-α, NF-κB p65/Rela and NF-κB2 were significantly increased in the hypertension combined with HHcy group compared with the WKY group (p < 0.05)." (PMID 34603014, 2021). "In the PPI network, we observed that IL-6, CCL2, IL-1β, MMP-2, and MMP-9 were the hub targets of GZD for improving hypertension." (PMID 33906674, 2021). "Monocyte recruitment is the key factor in the development of vascular inflammation, followed by adhesion molecules (VCAM-1 and ICAM-1), inflammatory factors (TNF-α and IL-6), and chemokines (CCL2, CXCL5, CXCL8, and CXCL10) released during hypertension." (PMID 34335249, 2021).
Hypertension (continued). "Four studies provided data on the IL-6 difference between HSD versus LSD and were included in the meta-analysis (n = 264, weighted age 67.1 ± 8.7 years, men 60%, hypertension 45.8%)." (PMID 34444792, 2021). "It is worth noting that both IL-6 and TNF-α were increased in hypertension combined with HHcy rats, among which HHcy was the contributor for increased IL-6, while hypertension was the main factor for increased TNF-α." (PMID 34603014, 2021). "What’s more, the aorta protein relative expression levels of IL-6 and TNF-α were also significantly increased in the hypertension combined with HHcy group compared with the WKY group (p < 0.05)." (PMID 34603014, 2021). "Plasma levels of IL-6 and TNF-α were also measured in a population of elderly subjects with hypertension undergoing aerobic training or aerobic and resistance training for 10 weeks." (PMID 32295038, 2020). "Mercury-exposed citizens, especially those with hypertension, had significantly higher concentrations of inflammatory cytokines TNF-α, IL-2, IL-6 and anti-inflammatory cytokine IL-10 as compared to the unexposed population." (PMID 33083327, 2020). "In this review, we focused on the central and peripheral effects of ADAM17-mediated shedding of inflammatory cytokines such as IL-6, TNF-α, and FKN, and their possible role in hypertension." (PMID 32848763, 2020). "An increase of the IL-6 and TNF-α levels in the blood plasma was observed among the participants with hypertension in comparison with normotensive participants." (PMID 33083327, 2020). "Inflammatory factors, such as C-reactive protein, IL-1β, IL-6, TNF-α, and ROS, are involved in the development and consolidation of hypertension by strengthening the stiffness of vessels and endothelial dysfunction." (PMID 33419373, 2020). "Bautista L.E., Vera L.M., Arenas I.A., Gamarra G. Independent associationbetween inflammatory markers (C-reactive protein, interleukin-6, and TNF-α) and essential hypertension." (PMID 33659786, 2020). "Mean levels of IL-6, MCP-1, PWV, and IMT of patients with young-onset hypertension and normotensive controls." (PMID 31655529, 2019). "Azra Mahmud also founded that arterial stiffness is related to systemic inflammation including TNF-α, IL-6 and hs-CRP in essential hypertension." (PMID 29433526, 2018). "Examination of downstream mediators of IL-6 signaling, such as STAT3, has also revealed important insight into the role of IL-6 in experimental hypertension." (PMID 29186034, 2017). "The CMV IgG antibody titers were positively correlated with arterial BP, greater grade of hypertension and hypertensive TOD, and CRP and IL-6 levels." (PMID 28837559, 2017). "Cytokine/chemokine IL-1ra, IL-6, IL-13, IFN-γ, MCP-1, MIP-1β levels and metabolic hormone such as GLP-1 levels significantly (p < 0.05) decreased in pregnant women with hypertensive disorders as compared with the HP group." (PMID 28348564, 2017). "In the hypertension disorders group, significantly SBP is negatively correlated with IL-6 (r = 0.447, p < 0.0133) and IL-10 (0.556, p < 0.0048)." (PMID 28348564, 2017). "Essential hypertension (EH) patients exhibited a marked increase in CMV IgG antibody, CRP, TNF-α, and IL-6 levels." (PMID 28837559, 2017). "The aim of the current study was to examine the effects of treatment of hypertension and CAD on serum levels of IL-6, IL-8, TGF-β and TNF-α." (PMID 28033321, 2016). "Correlations among age, weight, BMI, IL-6, IL-8, TNF-α and TGF-β within group 2 (patients with hypertension and CAD)." (PMID 28033321, 2016). "Previous investigations also confirm that serum levels of IL-6, IL-8, TGF-β and TNF-α were altered in the patients suffering from hypertension and CAD." (PMID 28033321, 2016).